BHLHE40 (basic helix-loop-helix family member e40)
Description:
Transcriptional repressor involved in the regulation of the circadian rhythm by negatively regulating the activity of the clock genes and clock-controlled genes. Acts as the negative limb of a novel autoregulatory feedback loop (DEC loop) which differs from the one formed by the PER and CRY transcriptional repressors (PER/CRY loop). Both these loops are interlocked as it represses the expression of PER1/2 and in turn is repressed by PER1/2 and CRY1/2. Represses the activity of the circadian transcriptional activator: CLOCK-BMAL1|BMAL2 heterodimer by competing for the binding to E-box elements (5'-CACGTG-3') found within the promoters of its target genes. Negatively regulates its own expression and the expression of DBP and BHLHE41/DEC2. Acts as a corepressor of RXR and the RXR-LXR heterodimers and represses the ligand-induced RXRA and NR1H3/LXRA transactivation activity. May be involved in the regulation of chondrocyte differentiation via the cAMP pathway. Represses the transcription of NR0B2 and attenuates the transactivation of NR0B2 by the CLOCK-BMAL1 complex. Drives the circadian rhythm of blood pressure through transcriptional repression of ATP1B1 in the cardiovascular system.
Synonyms: bHLHb2; DEC1; SHARP-2; SHARP2; STRA13; Clast5; HLHB2; Stra14
Tractability: PROTAC: UniProt records ubiquitination sites on it; ubiquitination databases record sites on it; its protein half-life has been measured.
Gene: Protein-coding gene on chromosome 3 (4,978,715 to 4,985,323, forward strand). Ensembl gene ENSG00000134107.
Subcellular location: Cytoplasm; Nucleus
Subcellular location (Human Protein Atlas): Nuclear bodies
Pathways (Reactome):
Circadian clock: BMAL1:CLOCK,NPAS2 activates circadian expression; Phosphorylated BMAL1:CLOCK (ARNTL:CLOCK) activates expression of core clock genes
Gene Ontology:
Molecular function: bHLH transcription factor binding; DNA-binding transcription factor activity, RNA polymerase II-specific; DNA-binding transcription repressor activity, RNA polymerase II-specific; E-box binding; protein binding; protein domain specific binding; protein heterodimerization activity; protein homodimerization activity; sequence-specific double-stranded DNA binding; DNA-binding transcription factor activity; MRF binding; RNA polymerase II cis-regulatory region sequence-specific DNA binding; RNA polymerase II-specific DNA-binding transcription factor binding; DNA binding; protein dimerization activity
Biological process: circadian regulation of gene expression; circadian rhythm; negative regulation of DNA-templated transcription; negative regulation of transcription by RNA polymerase II; anterior/posterior pattern specification; entrainment of circadian clock by photoperiod; regulation of circadian rhythm; regulation of DNA-templated transcription; regulation of neurogenesis
Cellular component: cytoplasm; nuclear body; nucleus; chromatin
Genetic constraint (gnomAD): Loss-of-function variants: 3 observed, 35.46 expected, observed/expected ratio (o/e) 0.0846, 90% interval 0.038 to 0.22. The upper end of that interval is the gene's LOEUF score, 0.22, which puts it in group 1 of 6, group 1 being the genes least tolerant of losing a copy. Missense variants: 486 observed, 544.99 expected, observed/expected ratio (o/e) 0.89, 90% interval 0.83 to 0.96. Synonymous variants: 236 observed, 220.9 expected, observed/expected ratio (o/e) 1.07, 90% interval 0.96 to 1.19.
Homologues: Orthologues: chimpanzee BHLHE40 (100% identical), macaque BHLHE40 (97% identical), dog BHLHE40 (95% identical), pig BHLHE40 (95% identical), mouse Bhlhe40 (90% identical), rat Bhlhe40 (90% identical), guinea pig BHLHE40 (75% identical), zebrafish bhlhe40 (58% identical), tropical clawed frog bhlhe40 (52% identical), Drosophila melanogaster E(spl)mgamma-HLH (13% identical), Drosophila melanogaster E(spl)mbeta-HLH (13% identical), Drosophila melanogaster cwo (11% identical), and 6 more. Paralogues in human: BHLHE41 (43% identical), HEY2 (17% identical), HEYL (15% identical), HES1 (15% identical), HEY1 (15% identical), HES6 (15% identical), HES4 (14% identical), HELT (13% identical), HES5 (12% identical), HES3 (11% identical), HES7 (11% identical), HES2 (10% identical).
Diseases named in the same sentence as BHLHE40 in open-access papers:
BHLHE40 is named in the same sentence as 131 diseases in open-access papers, as found by Europe PMC text mining. Sharing a sentence is not in itself a finding about the gene and the disease. The quoted sentences say what the papers report.
breast carcinoma (17 papers, 2015 to 2025). "For instance, in certain types of cancer like gastric cancer, breast cancer, and colorectal cancer, the expression level of BHLHE40 is significantly increased." (PMID 40046513, 2025). "Cluster C2 of macrophages showed upregulation of BHLHE40, which helps drive breast cancer metastasis, and those expression levels correlated inversely with survival." (PMID 35874785, 2022). "For example, BHLHE40 directly interacts with estrogen receptor α to suppress the proliferation of ER-positive breast cancer cells." (PMID 34917665, 2021). "Paradoxically, BHLHE40 is also upregulated in many cancers, such as in gastric cancer and in breast cancer." (PMID 32577154, 2020). "Overexpression of HIF-1α in 293T cells caused a 2-3 fold increase in BHLHE40 transcription, while BHLHE40 expression was shown to correlate with hypoxia and angiogenic markers such as HIF1α, angiogenin and VEGFD in breast cancer tissue." (PMID 32577154, 2020). "BHLHE40 promotes PI3K/Akt/mTOR activation in breast cancer, activating tumor progression, but suppresses STAT1 expression in clear cell carcinoma, triggering tumor suppression." (PMID 32577154, 2020). "In two studies of about 1200 breast cancer patients each, BHLHE40 was one of multiple markers predicting disease outcome and metastatic risk." (PMID 32577154, 2020). "Investigations of 253 breast cancer patients demonstrated an increase in BHLHE40 expression from normal to in situ as well as invasive breast carcinoma." (PMID 32577154, 2020). "Taken together, these results suggest that BHLHE40 plays a role in promoting primary tumor growth and spontaneous distant metastasis of breast cancer cells." (PMID 30285805, 2018). "BHLHE40 knockdown significantly reduced primary tumor growth and lung metastasis in orthotopic xenograft and experimental metastasis models of breast cancer." (PMID 30285805, 2018). "Global gene expression analysis and public database mining were performed to identify signaling pathways regulated by BHLHE40 in breast cancer." (PMID 30285805, 2018). "Orthotopic xenograft and experimental metastasis (tail vein injection) mouse models were used to analyze the role of BHLHE40 in lung metastasis of breast cancer." (PMID 30285805, 2018). "This study aimed to elucidate the function of BHLHE40 in the metastatic process of breast cancer cells." (PMID 30285805, 2018). "In this study, we provide evidence which suggests that BHLHE40 is a pro-metastasis factor in breast cancer cells which promotes tumor cell survival and migration by modulating exosomic secretion of heparin-binding epidermal growth factor (HBEGF)." (PMID 30285805, 2018). "Having established a role for BHLHE40 in distant metastasis of breast cancer cells in vivo, we sought to identify the specific cellular processes that require BHLHE40 activity." (PMID 30285805, 2018). "In breast cancer, expression of BHLHE40 correlated with invasiveness and its gene silencing in breast cancer cell lines resulted in reduced invasiveness." (PMID 27096627, 2016). "Conversely, secretory CLU knockdown enhanced DNA damage-induced cell death in breast cancer cells, suggesting that BHLHE40 promoted cell survival by up-regulating secretory CLU to reduce the apoptotic response to DNA damage, providing insights into their roles in breast cancer progression." (PMID 40046513, 2025). "Notably, BHLHE40 plays a pivotal role in the pathogenesis of colorectal cancer, breast cancer, and gastric cancer." (PMID 37377917, 2023). "Besides, BHLHE40 confers a pro-survival and pro-metastatic phenotype to breast cancer cells by modulating HBEGF secretion." (PMID 36463222, 2022). "Moreover, the basic helix-loop-helix transcription factor BHLHE40 was shown to be induced by hypoxia, and BHLHE40 knockdown reduced the release of exosomes in breast cancer cells." (PMID 35039054, 2022). "At least 5 individual studies have indicated that BHLHE40 is upregulated in breast cancer tissue." (PMID 32577154, 2020).
breast carcinoma (continued). "To define the role of BHLHE40 in breast cancer metastasis, we examined the effect of its knockdown (KD) by a shRNA lentiviral construct on spontaneous lung metastasis of orthotopic xenograft tumors derived from a lung metastasis-enriched subline (LM) of breast cancer MDA-MB-231 cells." (PMID 30285805, 2018). "However, the mechanism of action and downstream targets of BHLHE40 in breast cancer cells is largely unknown." (PMID 30285805, 2018). "They report a similar downregulation of PER1, PER2, CRY2, and HLF, in breast cancer samples while CLOCK, ARNTL(BMAL1), and BHLHE40 levels remained relatively unchanged." (PMID 38319971, 2024). "It has been reported that BHLHE40 can promote SNAI1 and SNAI2 expression and inhibit the expression of CLDN1, CLDN4, and CDH2 in breast cancer, promoting the migration and invasion of tumor cells." (PMID 37377917, 2023). "For example, Bhlhe40 facilitates PI3K/Akt/mTOR activation and triggers tumor progression in breast cancer, whereas it represses STAT1 expression and activates tumor suppression in clear cell carcinoma." (PMID 33987177, 2021). "In breast cancer cells, clusterin (CLU) was identified as a novel target gene of BHLHE40 and suppressed DNA damage-induced cell death." (PMID 32577154, 2020). "The function of nuclear BHLHE40 was apparent from other studies, where nuclear BHLHE40 was up-regulated in MCF-7 estrogen receptor positive breast cancer cells upon paclitaxel treatment, suggesting that nuclear BHLHE40 prevent tumor progression." (PMID 32577154, 2020). "This trend was also consistent across a number of cancers: in particular, highly rewired TFs such as BHLHE40, JUND, and MYC behaved similarly in lung, liver, and breast cancers." (PMID 32728046, 2020). "Thus, BHLHE40 is consistently upregulated in breast cancer, irrespective of the subtype of breast cancer investigated." (PMID 32577154, 2020). "BHLHE40 is upregulated in breast cancer compared to normal breast tissue – and although the data presented do not refer to the localization of BHLHE40, accompanying immunohistochemical staining shows both nuclear as well as cytoplasmic staining in the tumor tissue." (PMID 32577154, 2020).
pancreatic cancer (12 papers, 2020 to 2025). "Our outcomes showed that cancer-associated immune cells, like Th2, NK CD56bright cells, positively linked with BHLHE40 expression in pancreatic cancer." (PMID 37773521, 2023). "In the same way, we found that the expression of hsa-miR-15a-5p, has-miR-16-5p and has-miR-454-3p in pancreatic cancer were negatively associated with BHLHE40." (PMID 37773521, 2023). "Nevertheless, the pro-cancer biological functions and underlying molecular mechanisms of BHLHE40 for pancreatic cancer and its unique microenvironment are unclear." (PMID 37773521, 2023). "PDC, TFH, Tgd, cytotoxic cells, B cells and Th17 cells were negatively associated with BHLHE40 levels in pancreatic cancer." (PMID 37773521, 2023). "Low expression of BHLHE40 is associated with an enrichment of various immune cell types, indicating its role in immune suppression and immune escape in pancreatic cancer." (PMID 38139352, 2023). "Silencing BHLHE40 showed favorable antitumor efficacy, underlining BHLHE40 as a hopeful predictor and potential target for pancreatic cancer therapy." (PMID 37773521, 2023). "Nevertheless, the expression of BHLHE40 in pancreatic cancer is poorly defined, and only the molecular mechanism of BHLHE40 in tumor-associated neutrophils (TANs) has been reported in pancreatic cancer." (PMID 37773521, 2023). "The present study indicated that ITGA2, ITGA3, ADAM9, and BHLHE40 were potential target genes associated with the development of pancreatic cancer." (PMID 37377917, 2023). "Analysis of the Cancer Genome Atlas (TCGA) also showed that low expression of BHLHE40 was associated with favorable prognosis in pancreatic cancer patients." (PMID 32577154, 2020). "In summary, our data showed that ceRNA involved in the regulation of BHLHE40 contributes to the promotion of immunosuppressive response in pancreatic and is expected to be a diagnostic marker and potential immunotherapeutic target for pancreatic cancer." (PMID 37773521, 2023). "In addition, BHLHE40 was identified as a potential diagnostic marker for distinguishing pancreatic cancer from healthy pancreatic tissues in ROC curve analysis." (PMID 37773521, 2023). "For instance, in pancreatic cancer, BHLHE40 has been identified as a key regulator of angiogenic neutrophil development." (PMID 41203997, 2025). "BHLHE40 knockdown significantly reduces the metastasis and proliferation of pancreatic cancer cells." (PMID 40959280, 2025). "This study investigates the role of basic helix‐loop‐helix transcription factor 40 (BHLHE40) in pancreatic cancer (PCa), revealing its upregulation in tumor due to increased chromatin accessibility and mTOR pathway activity." (PMID 38064101, 2024). "In analyses of TCGA database, BHLHE40 significantly predicted poor prognosis and lower survival time in patients with pancreatic cancer (HR 1.83, p = 0.005)." (PMID 37377917, 2023). "BHLHE40 was identified as one of a number of core genes involved in the development of pancreatic cancer." (PMID 37377917, 2023). "Here, our results showed the possible involvement of BHLHE40 in modulating the TME of pancreatic cancer." (PMID 37773521, 2023). "In short, elevated expression of BHLHE40 in the vast majority of immune cells contributed to the occurrence of poor prognosis in pancreatic cancer patients." (PMID 37773521, 2023). "Altogether, we demonstrated the potential function of BHLHE40 as a regulator of tumor progression and its value as a direct therapeutic target and a prognostic marker of pancreatic cancer." (PMID 37773521, 2023). "To further clarify the pro-oncogenic function of BHLHE40 on pancreatic cancer, we have firstly successfully established a BHLHE40 knockdown pancreatic cancer cell line, PATU-8988 and PANC-1." (PMID 37773521, 2023). "In parallel, we separated pancreatic cancer patients into high and low expression groups depending on the BHLHE40 expression." (PMID 37773521, 2023).
pancreatic cancer (continued). "IHC staining of BHLHE40 in PDAC tissues from pancreatic cancer patients showed that BHLHE40 located in the nucleus was highly expressed in tumor tissues compared to the normal tissue and its highly expressed in the ductal cells, stroma cells, immune cells." (PMID 37773521, 2023). "In sum, this work described the clinical pertinence, tumor immune microenvironment characterization, biological functions and molecular pathways of BHLHE40 in pancreatic cancer." (PMID 37773521, 2023). "Among the three candidate miRNAs, only miR-15a-5p was reported to have a relevant oncogenic role in pancreatic cancer, hence we concluded that miR-15-5p was the most probable upstream of BHLHE40." (PMID 37773521, 2023). "Here, we focused on pancreatic cancer in which BHLHE40 was upregulated and connected with poor OS in different subgroups, such as race, age, alcohol history, residual tumor, pathologic stages, and gender." (PMID 37773521, 2023). "miR-15a-5p is known to target BHLHE40 and the downregulation of miR-15a leads to an immune-suppressive microenvironment in pancreatic cancer." (PMID 38139352, 2023). "For this sake, it is particularly essential to determine the connection between the expression of BHLHE40 and the degree of immune cell infiltration in pancreatic cancer." (PMID 37773521, 2023). "By functional enrichment we identified that BHLHE40 potentially exerts a critical role in the TME of pancreatic cancer." (PMID 37773521, 2023). "This study discovered the potential molecular pathways by which BHLHE40 influences pancreatic cancer malignant progression." (PMID 37773521, 2023). "It implies that BHLHE40 possesses the function of suppressing immune response and increasing immune escape in pancreatic cancer." (PMID 37773521, 2023). "In our forthcoming work, we intend to elucidate the regulatory role of BHLHE40 in T cells, which is thought to promote malignant progression of pancreatic cancer by suppressing anti-neoplastic inflammatory responses." (PMID 37773521, 2023). "It implies that BHLHE40 plays a crucial role in promoting malignant progression of pancreatic cancer in many clinical features." (PMID 37773521, 2023). "In sum, BHLHE40 exerts an influential role in boosting the malignant progression of pancreatic cancer." (PMID 37773521, 2023). "Prior investigations have informed that BHLHE40 in TANs is essential for pancreatic cancer cell proliferation, migration and the growth ability of CD8+ T cells but did not explore the underlying mechanisms and biological functions of BHLHE40 in cancers." (PMID 37773521, 2023). "Other studies, however, showed increased cytoplasmic BHLHE40 in pancreatic cancer –supporting a tumor suppressive role for nuclear BHLHE40." (PMID 32577154, 2020). "After clarifying the function of BHLHE40 in promoting malignant progression of pancreatic cancer cells, in order to explore how BHLHE40 is upregulated in pancreatic cancer, we are keenly interested in ceRNAs regulatory mechanisms among many potential mechanisms." (PMID 37773521, 2023). "In addition, we explored and validated the FGD5-AS1/miR-15a-5p axis as a potential upstream regulatory mode for high expression of BHLHE40 in pancreatic cancer." (PMID 37773521, 2023). "Subsequent, spearman correlation analysis observed that higher expression of BHLHE40 might be involved in immunosuppression of pancreatic cancer." (PMID 37773521, 2023). "Meanwhile, we revealed that knockdown of BHLHE40 could augment the apoptosis level of pancreatic cancer cells by flow cytometry assay." (PMID 37773521, 2023). "Furthermore, to investigate the impact of BHLHE40 in the TME on pancreatic cancer survival, we organized an analysis of the potential linkage of BHLHE40 in various immune cell subpopulations on pancreatic cancer prognosis." (PMID 37773521, 2023).